COL1A1 (collagen type I alpha 1 chain)
Diseases named in the same sentence as COL1A1 in open-access papers (continued):
Sharing a sentence is not in itself a finding about the gene and the disease.
Myocardial fibrosis (44 papers, 2014 to 2025). "Numerous studies have highlighted the association between an elevated Col1a1/Col3a1 ratio and myocardial fibrosis." (PMID 39592912, 2025). "Fibrotic and extracellular remodeling markers Tgfβ1, Mmp2, Timp1, Col1a1, Col3a1, fibronectin and vimentin demonstrated a complex balance underlying myocardial fibrosis at different overload stages." (PMID 31181097, 2019). "The myocardial fibrosis marker gene Col1a1, Col3a1, and Tgfb1 were downregulated, correlated with the reversal of Piezo1." (PMID 40344385, 2025). "For example, in mice with myocardial fibrosis post‐myocardial infarction, Col1a1 levels were significantly increased, whereas Col3a1 levels decreased, resulting in an elevated Col1a1/Col3a1 ratio." (PMID 39592912, 2025). "The expression of Col1a1, a primary component of the extracellular matrix and a marker for myocardial fibrosis, was strongly induced after 48 h of hyperoxia at P7." (PMID 41516025, 2025). "We found that tRF-Glu-CTC-013 reduced the expression of Tgfb1, Col1a1, Col3a1 and Fn1, thereby inhibiting myocardial fibrosis." (PMID 40520901, 2025). "As a result of cardiomyocyte injury caused by MI, the heart failure marker gene Anp upregulated significantly, accompanied with the upregulation of myocardial fibrosis marker Col1a1." (PMID 40344385, 2025). "Histological analyses by Sirius red staining showed exaggerated myocardial fibrosis in Gadlor-EV-treated mice, which was confirmed by qPCR of Col1a1 and Col3a1 mRNA expression in the myocardium." (PMID 39281699, 2024). "Some studies on the mechanism by which Stat3 exacerbates myocardial fibrosis showed that Stat3 is bound with COL1A1 and COL3A1 promoter and activates their transcription." (PMID 37891701, 2023). "Masson's trichrome staining and immunohistochemical staining for Col1A1 was used to observe the degree of myocardial fibrosis at 28 days after patch implantation." (PMID 34485415, 2021). "Knockdown in H9c2 cells, utilising siRNA of either LOXL2 or ETFβ, revealed a decrease in the expression of Collagen Type I Alpha1 (COL1A1), a marker known to contribute to enhanced myocardial fibrosis." (PMID 32703998, 2020). "With the progression from AVMC to DCM, the severity of myocardial fibrosis significantly increased accompanied by up-regulation of COL1-A1, COLA3-A1, MMP9 and ratio of MMP9/TIMP-1 but down-regulation of TIMP-1." (PMID 25547181, 2014). "Combining these findings with our study results, it is suggested that Fmod may contribute to myocardial fibrosis in RCFs by increasing the Col1a1/Col3a1 ratio, thereby implicating Fmod in the pathological process of diabetic cardiomyopathy." (PMID 39592912, 2025). "Besides, the mRNA expression of myocardial fibrosis‐related genes (Col1a1, Col5a1, and Mmp2) was reinstated in mice administered T‐5224." (PMID 40184586, 2025). "Moreover, our results revealed that berberine dose‐dependently reduced myocardial fibrosis, which was supported by a decrease in fibrosis area and reduced expression of fibrosis‐related markers (COL1A1, COL3A1, TGF‐β and α‐SMA)." (PMID 38894630, 2024). "Experimental evidence showed that Ang II could significantly reduce the expression of miR-133a and miR-29b in cardiomyocytes and increase the expression of its target gene Col1A1, leading to myocardial fibrosis." (PMID 38799791, 2024). "The comparison between the T1DM and T2DM mice revealed an increase in myocardial fibrosis in the first group of animals, as confirmed with RT-PCR on freshly isolated CMs, in which the expressions of Col1a1, Col1a2 and Col3a1 were found to be higher in the T1DM mice compared to in the T2DM mice." (PMID 36674648, 2023). "In addition, transcript levels of a selected number of genes involved in myocardial fibrosis, namely, Ctgf (Ccn2), Postn, Col1a1, Col5a2, and Timp, quantified by RT-PCR, were also increased in the Pdgfra-Cre:LmnaF/F mouse hearts." (PMID 35891706, 2022).
Myocardial fibrosis (continued). "Recent data demonstrate a relationship between miR-133a and collagen 1A1 (Col1A1), suggesting that myocardial fibrosis occurring in Ang-II-dependent hypertension is regulated by the downregulation of miR-133a and miR-29b through the modulation of Col1A1 expression." (PMID 28751931, 2017). "Importantly, our study demonstrated that Fmod overexpression in RCFs elevated the Col1a1/Col3a1 ratio, which may better elucidate how Fmod influences myocardial fibrosis." (PMID 39592912, 2025). "In addition, we selected CD11b and Col1a1, the biomarkers for a variety of inflammatory/immune cells and collagen deposition in extracellular matrix, to validate the inflammatory cells infiltration and myocardial fibrosis levels after myocardial injury." (PMID 40893347, 2025). "Then the myocardial fibrosis increased and survival rate decreased in mice after neutralizing IL-22, accompanied by a decline in Th22 cell number, reduced IL-22, diminished IL-22R expression and increased indicators of myocardial fibrosis such as COL1-A1, COL3-A1, MMP9." (PMID 25547181, 2014). "Meanwhile, the mRNA levels of Col1a1 and Col5a1 (key genes involved in collagen synthesis) also confirmed that CDPs significantly attenuated DOX-induced myocardial fibrosis." (PMID 41462661, 2025). "Overexpression of COL1A1 and COL1A2 in the ECM–receptor interaction pathway led to myocardial fibrosis, as demonstrated in the CHF group of our experiment." (PMID 40785031, 2025). "Treatment with miR-214-3p agomir reduced the myocardial expression of COL1A1 and COL3A1 and attenuated myocardial fibrosis in mice." (PMID 41166051, 2025). "Targeting proteins directly involved in collagen synthesis, such as collagen type l alpha (COL1A1) and COL3A1, is an alternative way of targeting excessive collagen synthesis in myocardial fibrosis." (PMID 41166051, 2025). "The aggravated cardiac dysfunction and myocardial fibrosis were further supported by increased mRNA levels of ANP, BNP, Col1a1, and Col3a1 in RTN3CKO mice treated with J2." (PMID 38420163, 2024). "Immunohistochemical staining showed that the CTGF- and COL1A1-labeled fibers in the myocardial interstitium of db/db were significantly increased, suggesting that HFD-induced myocardial fibrosis in db/db mice." (PMID 35235096, 2023). "While a neutralizing antibody against IL-22 led to increased COL1-A1, COL3-A1, MMP9 expression, and intensified myocardial fibrosis in DCM mice, suggesting that IL-22 protects the myocardium by inhibiting myocardial fibrosis." (PMID 36827455, 2023). "Histological analyses revealed increased myocardial fibrosis in Musclin KO mice in response to TAC compared to WT mice, which was accompanied by upregulation of pro-fibrotic genes like Postn, Col1a1, Col3a1 and Fn1." (PMID 35013221, 2022). "Myocardial fibrosis was evaluated by the Masson staining assay, Sirius red staining assay, and immunohistochemical assay for the expressions of α-SMA and COL1A1." (PMID 35721103, 2022). "We observed that the degree of myocardial fibrosis gradually increased with the progression from AVMC to DCM, accompanied by up-regulation of COL1-A1 and COLA3-A1." (PMID 25547181, 2014). "In addition to the obvious myocardial fibrosis observed by histopathology, the mRNA expression of profibrotic TGF-β, CTGF, Col1a1 and Col3a1 were elevated in piglets and cardiomyocytes with MYH7 R453C mutation." (PMID 38862020, 2024). "Meanwhile, the upregulated mRNA levels of FN, CTGF, Col1a1 and Col3a1 in the TAC + rAAV9‐miR + SRI group further indicated that SRI‐011381 administration significantly reversed the inhibitory effect of rAAV9‐POSTN‐miR‐425‐5p on myocardial fibrosis." (PMID 39527465, 2024). "The mRNA expression levels of collagen (COL1A1 and COL3A1) and α-SMA, which are markers of myocardial fibrosis, were significantly elevated in the Ang II group compared to the saline group, but muscone treatment significantly suppressed the elevated mRNA levels of α-SMA, COL1A1, and COL3A1." (PMID 38158445, 2023).
Myocardial fibrosis (continued). "Consistent with the protective effect ofNAC on cardiac pathophysiological changes, real-time RT-PCR analysis of the mRNAexpressions that related to cardiac hypertrophy and myocardial fibrosis, such asα-MHC, β-MHC, ANP, BNP, Col1a1, Col3a1, Mmp2,and Mmp9, also showed the similar trend." (PMID 27443826, 2016). "Therefore, we observed the contents of TGF-β, COL1A1, BNP proteins in heart tissues, and investigated pathological sections of the cardiac of mice to observe the therapeutic effect of liraglutide in respect to myocardial fibrosis and heart failure." (PMID 40765557, 2025).
heart failure (40 papers, 2016 to 2026). Inability of the heart to pump blood at an adequate rate to meet tissue metabolic requirements. "A recent study showed that a plasma COL1A1 concentration >256.5 ng/mL was associated with poor survival from heart failure in heart transplant recipients." (PMID 35602164, 2022). "Also, an increased abundance of peptides from the COL1A1 termini was found associated with death in the context of heart failure, while peptides from the middle part were decreased." (PMID 39740102, 2025). "Previous reports have demonstrated that Col1a1/1a2 upregulation plays a crucial role in alleviating cardiac burden caused by adrenaline elevation, as demonstrated in a study on alleviating adrenaline-induced heart failure in mice." (PMID 38283372, 2023). "Furthermore, CD3ε-/- mice had lower mRNA levels of Nppb, which encodes brain natriuretic peptide (BNP), a marker of heart failure, as well as lower levels of Col1a1, a fibrosis marker, compared to WT mice." (PMID 34745139, 2021). "Furthermore, COL1A1 content ≥ 256.5 ng/ml in plasma was found to be associated with poor survival within 1 year of heart transplantation from heart failure [hazard ratio (HR) 7.4, 95% confidence interval (CI) 3.5 to 15.8, Log-rank p value < 1.0 × 10− 4]." (PMID 31902369, 2020). "POSTN(+)CD68(+)COL1A1(+) cells were clearly observed in human tissues from patients with heart failure, indicating the presence of the MMT in human hearts." (PMID 39261656, 2024). "A multi-level transcriptomics (mRNA, lncRNA, miRNA) sequencing of left ventricular samples from patients with end-stage heart failure identified COL1A1 as a biomarker for the prognosis of heart failure, and it was also verified at the plasma level." (PMID 38921668, 2024). "Deletion of RalGAPα1 also exacerbated TAC-induced cardiac remodeling with upregulation of cardiac fibrosis and increased expression of heart failure markers such as Anp, Bnp, Col1a1 and Col3a1 in the RalGAPα1-cKO hearts as compared to the control hearts." (PMID 35879328, 2022). "COL1A1 is the major component of fibrillar collagen found in most connective tissues, including cartilage, and was identified as a potential biomarker for heart failure progression." (PMID 34680994, 2021). "Furthermore, we observed the proportion of markers associated with fibroblasts (VIM, POSTN, DDR2, THBS4, COL1A1, COL1A2, FN1) were significantly higher in heart failure than the control group in the human data, which were consistent with that in mice." (PMID 36805782, 2023). "Based on the inflammatory and fibrotic markers commonly observed in response to myocardial infarction and development of heart failure, we assessed the expression of mRNA for Tnfa, Il1b,Il6, Il18, Ccl2, Ccl3, Cxcl1, Cxcl2, Col1a1, Col3a1, Postn, and Tlr4 at 1 and 3 months." (PMID 35411847, 2022). "In addition, HC treatment significantly decreased Nppa, Nppb, Col1a1, and Col3a1 levels, known as major heart failure markers." (PMID 34679760, 2021). "Consistently, collagen type 1, alpha 1, recently identified as a marker in human heart failure progression related to tissue fibrosis and encoded by the gene Col1a1, was not differentially expressed in Fgf23fl/fl/cre+ mice compared to age-matched controls." (PMID 35118076, 2021). "The increased ratio of Col1a1 to Col3a1 at the protein level could be a factor in the stiffness and resistance to stretch in both in HFpEF and HFrEF in different heart failure and hypertrophy forms." (PMID 31380269, 2019). "The heart weight/body weight ratio was significantly higher in Bmx/CA mice, and expression levels of genes related to heart failure such as Nppa and Nppb as well as fibrosis marker gene Col1a1 were also higher in the heart of Bmx/CA mice compared with Ctrl mice." (PMID 27146149, 2016).
heart failure (continued). "Inclusively, the expression patterns of the most proteins (MMP-2, Col1a1, Col3a1, N-Cadherin, β-Catenin, CnA, RyR, SERCA2 and PTGS2) in human heart failure are consistent with the discoveries above in the Cre recombinase-induced cardiotoxicity model." (PMID 36834504, 2023). "Upregulated genes in Vehicle include NPPB, COL1A1, FMOD, LOX and MMP9, among others, some of which are related with pro-fibrotic processes and heart failure." (PMID 37342444, 2023). "The molecular indicators of heart failure (ANP and BNP) and fibrosis (Col1a1 and Col3a1) were elevated in the RV of PAB rats compared to sham rats." (PMID 37932744, 2023). "For example, Col1a1 is upregulated in the MCT RV, consistent with increased fibrosis in the right ventricle and heart failure." (PMID 36388115, 2022). "Intriguingly, we observed a drastic decrease in the Myh6/Myh7 ratio but no change in the expression of Nppa, Col1a1, and Postn in cKO hearts at the early stage, consistent with no cardiac fibrosis or heart failure at this time." (PMID 38201239, 2023). "The roles of COL1A1 and FN1 in heart failure were previously well explored." (PMID 37450589, 2023). "Moreover, the cardiac mRNA expression of the hypertrophy and heart failure markers Anp and Bnp and the fibrosis marker Col1a1 were not affected by PD-L1 inhibition." (PMID 39834851, 2024).
dermatofibrosarcoma protuberans (39 papers, 2011 to 2025). Dermatofibrosarcoma protuberans (DFSP) is a rare infiltrating soft tissue sarcoma, generally of low grade malignancy, arising from the dermis of the skin and characteristically associated with a specific chromosomal translocation t(17;22). "In the dermatofibrosarcoma protuberans, the fusion of the collagen type I alpha 1 (COL1A1) gene with the PDGFB gene caused PDGFBB and its receptor (PDGFRβ) autocrine stimulation and cell proliferation." (PMID 38378786, 2024). "This fusion is highly reminiscent of the COL1A1‐PDGFB oncogene associated with dermatofibrosarcoma protuberans." (PMID 33830670, 2021). "The PDGF receptor inhibitor imatinib showed efficacy in COL1A1‐PDGFB‐positive dermatofibrosarcoma protuberans as adjuvant therapy, confirming the importance of the PDGF‐BB autocrine loop in tumour growth." (PMID 33830670, 2021). "The overexpression of a growth factor secondary to a gene fusion event is highly reminiscent of the COL1A1‐PDGFB translocation in dermatofibrosarcoma protuberans." (PMID 33830670, 2021). "For example, certain rearrangements, such as those involving ALK in inflammatory myofibroblastic tumors or COL1A1-PDGFB in dermatofibrosarcoma protuberans, are predictive of the response to tyrosine kinase inhibitors." (PMID 32351889, 2020). "A second MPNST was reclassified as fibrosarcomatous transformation of a dermatofibrosarcoma protuberans on discovery of the characteristic COL1A1‐PDGFB fusion." (PMID 32573957, 2020). "Imatinib was found to specifically target PDGFRB tyrosine kinase, and so its use was approved for treating COL1A1-PDGFRB-positive dermatofibrosarcoma." (PMID 32317857, 2020). "Imatinib has also shown antitumor effect in preclinical models of DFSP and giant-cell fibroblastoma, which are rare, recurrent, and infiltrative tumors of the dermis classically characterized by a COL1A1/PDGFB translocation." (PMID 31665941, 2019). "The equivalent pathognomonic COL1A1-PDGFB gene fusion found in human dermatofibrosarcoma protuberans was found in a dermatofibrosarcoma protuberans-like canine tumor, with the equivalent fusion found being COL3A1-PDGFB in the dog." (PMID 29218302, 2017). "Because COL1A1-PDGFB is highly specific to dermatofibrosarcoma protuberans, the detection is clinically helpful for the diagnosis." (PMID 28978917, 2017). "Dermatofibrosarcoma protuberans (DFSP) is a rare cutaneous-origin sarcoma associated with constitutive activation of the receptor tyrosine kinase (RTK) PDGFR by chromosomal rearrangement with the collagen gene COL1A1." (PMID 21772794, 2011). "In addition, we previously found a case of dermatofibrosarcoma protuberans that was positive for novel COL1A1 exon 14/PDGFB fusion." (PMID 28978917, 2017). "COL1A1-PDGFβ translocation is specific to dermatofibrosarcoma protuberans, where the abnormally fused COL1A1-PDGFβ gene directs formation of an abnormal combined (fusion) protein that researchers believe to ultimately function like the platelet-derived growth factor-beta protein." (PMID 25924890, 2015). "Among them, COL1A1::PDGFB fusion uterine sarcoma is a recently described entity that shares the same genetic alteration as dermatofibrosarcoma protuberans (DFSP)." (PMID 41463261, 2025). "More than 90% of all cases of dermatofibrosarcoma protuberans (DFSP) contain a translocation of the Collagen alpha-1(I) chain (COL1A1) with PDGFB, often in a supernumerary ring chromosome." (PMID 38611033, 2024). "The partial amplification pattern might be compatible with fusion of the involved genes, similar to cases described in dermatofibrosarcoma protuberans, with COL1A1::PDGFB or in case of EWSR1::NFATC2 fusion (EWSR1 pattern of FISH) in round cell sarcomas with EWSR1–non-ETS fusions." (PMID 39839837, 2024).